CCL2 (C-C motif chemokine ligand 2)
Diseases named in the same sentence as CCL2 in open-access papers (continued):
Sharing a sentence is not in itself a finding about the gene and the disease.
tumor (continued). "EGCG treatment decreased the levels of colony stimulating factor 1 (CSF-1) and CCL-2 within the tumor and hence reduced the infiltration of TAM-like M2 macrophages in the 4T1-bearing mice." (PMID 34948368, 2021). "Such infiltration was associated with the release of CCL2 and CCL5 chemokines in the tumor microenvironment." (PMID 34155342, 2021). "Lymphocyte homing and infiltration can also be altered by posttranslational nitrosylation of CCL2 to nullify its ability to recruit tumor specific cytotoxic T lymphocytes (CTLs) making it hard to implement immunotherapy using antigen specific T cells." (PMID 34987525, 2021). "Conceivably, local depletion of CCR2+ TAM, Treg and tumor cells as well as local neutralization of ligand CCL2 in TME will likely enhance anti-tumor arm of immunity." (PMID 34804061, 2021). "Monocyte chemotactic protein 1 (MCP-1, also termed CCL2) is produced by monocytes, fibroblasts, epithelial cells, and several tumor cells and plays an important role in the recruitment and activation of macrophages and monocytes during antitumor immunity." (PMID 33574842, 2021). "In the tumor microenvironment, CCL2 interacted with CCR2 on the surface of macrophages to mediate the chemotaxis of monocytes and TAM to facilitate cancer progression." (PMID 33891564, 2021). "Multiple cytokines and chemokines are described for monocyte and macrophage recruitment into the tumor such as CCL2 and CX3CL139." (PMID 34290311, 2021). "Similar to β-AR blocker, 6OHDA treatment also abolished the EE-induced CCL2 suppression in the Hepa1-6 tumor tissue." (PMID 34593796, 2021). "One underlying mechanism depends on the ECM stiffening-induced tumor cell and CAF production of macrophage chemoattractants, such as CCL2 (C-C Motif Chemokine Ligand 2) and CSF1 (Colony Stimulating Factor 1)." (PMID 34298680, 2021). "MDSC recruitment to the tumor is mediated by different chemokines, in particular C-C Motif Chemokine Ligand 2 (CCL2), CCL5 and CXCL5." (PMID 34572009, 2021). "CCL2 knockdown in primary tumor cells resulted in retarded tumor growth but earlier development of lung metastases." (PMID 34386431, 2021). "It is known that Notch signaling regulates many components in the tumor microenvironment, such as the expression of pro-inflammatory cytokines IL1β and CCL2, and plays an important role in effector T cell differentiation." (PMID 33466719, 2021). "Exosomes in hypoxic tumor areas contain large amounts of chemokines and immunomodulatory proteins, including CSF-1, CCL2, FTH, FTL, and TGF-β, which promote the differentiation of infiltrating myeloid cells toward an M2-like macrophage lineage." (PMID 34603327, 2021). "MDSCs are recruited to tumor sites through GM-CSF; monocyte chemoattractant protein 1 (MCP1); CXCL1, 2, 5, and 12; IL-8; CSF1; prokineticin 2 (Prok2); CCL2; S100A8/9; and other factors derived from the TME47,61,62." (PMID 34403220, 2021). "Previous study showed that CCL2 recruits immune suppressor cells MDSCs and TAMs to tumor sites by binding to CCR2 receptor." (PMID 34729117, 2021). "The expression levels of CCL2 in peripheral blood and tumor tissues were significantly lower in sh-NLRP7-treated and sh-USP10-treated mice than in control mice and higher in NLRP7-treated mice with USP10 knockdown." (PMID 33838681, 2021). "IL-6 favors PD-L1 upregulation, and reciprocally increases CCL2 tissue levels, resulting in an amplification loop that promotes monocyte infiltration, malignant cell proliferation and tumor survival." (PMID 34830209, 2021). "They originate from bone marrow-derived circulating monocytes and accumulate in the tumor due to the presence of M-CSF, GM-CSF, and CCL2 as well as other factors." (PMID 34795675, 2021). "There is evidence to indicate that miR-206 targets the VEGFA/CCL2 signaling pathway to inhibit tumor progression." (PMID 34697590, 2021).
tumor (continued). "The DAMPs released by tumours cells treated with CHK1i+LDHU in vivo are also likely to contribute to the recruitment of inflammatory macrophages as suggested by the increased CCL2 expression." (PMID 34359633, 2021). "There is still evidence indicates the correlation between PTEN loss on tumor cells and elevation of immunosuppressive markers like IDO1, FOXP3, CCL2, CSF1 ect.." (PMID 33874915, 2021). "CCL2 acts on CCR2 to advance the tumor, whereas, in CCR4, it acts to recruit cytotoxic T lymphocytes and exert an anticancer effect." (PMID 34445235, 2021). "They originate from the circulating monocytes that are recruited to TME, mostly by chemokines such as MCP-1/CCL2 and CSF-1 derived from tumor cells or mesenchymal stem cells, which were later polarized and denoted as TAMs." (PMID 33129234, 2021). "There is also evidence that high levels of CCL2 promote polarization of TAMs to an immune-regulatory phenotype, which is considered a consequence of tumor cell-mediated immune modulation." (PMID 34386431, 2021). "Treatment with trabectedin depleted monocytes and macrophages in several animal tumor models and resulted in reduced tumor growth, downregulation of neoangiogenesis, and production of IL-6, CCL2, and CXCL8." (PMID 33919517, 2021). "CCL2 and/or anti‐CCL2 antibody‐treated mice model and tumor growth rates showed that tumor volume and weight of CCL2 treated group increased faster and anti‐CCL2 antibody inhibited tumor progression." (PMID 34525267, 2021). "CCL2-induced tumor spreading and metastasis are regarded as important results of TAMs recruitment and polarization." (PMID 34386431, 2021). "Meanwhile, the blockade of the CCL2 signaling pathway resulted in decreased recruitment of inflammatory monocytes and macrophages in the tumor microenvironment, forming an immunosuppressive phenotype and conferred cancer cells proliferation." (PMID 34335756, 2021). "They demonstrated in a laboratory setting that treatment with DiDBV2-Fe produced a strong and selective tumor tropism in response to CCL2 secreted by U87MG tumor cells." (PMID 33561993, 2021). "A wide range of cells can produce CCL2, including tumour cells, endothelial cells, fibroblasts, epithelial cells, smooth muscle cells and myeloid cells." (PMID 34464477, 2021). "One of the best-characterized cytokines responsible for recruiting TAMs into the tumor is chemokine (C-C motif) ligand 2 (CCL2), also known as monocyte chemoattractant protein 1 (MCP-1)." (PMID 33968034, 2021). "Monocyte chemoattractant protein 1 (MCP-1) or CCL2, regulates monocyte migration and is frequently expressed as tumor cell-associated chemokine." (PMID 33924500, 2021). "Another molecule of particular importance in cancer development is the chemokine (C–C motif) ligand 2 (CCL2)—a key mediator of interactions between tumor and host cells, and also an essential participant in the development and maintenance of pain." (PMID 34575835, 2021). "The tumor-promoting activity of the MSCs in vivo was largely dependent on their capacity for enhanced production of CCL2, COX-2 and IL-6." (PMID 34830312, 2021). "For example, MDSCs are recruited to tumor locations by CCL2 and potentially CXCL1 and CXCL2, where direct contact with MCs or with histamine increases their inhibitory function." (PMID 34829729, 2021). "Next, we recurred to transplantable Hepa1-6 and H22 tumor models to confirm the tumor-suppressive effect of EE dependent on CCL2 modulation." (PMID 34593796, 2021). "The qRT-PCR results showed that EE housing led to a profound decrease of mRNA expression of CCL2 in both tumor cells and immune cells, including TAMs and G-MDSCs." (PMID 34593796, 2021). "Tumor cells can also induce CCL2 expression in TANs in a paracrine manner, resulting in a protective effect against chemotherapy." (PMID 34386431, 2021). "TAMs are mainly recruited from the periphery by chemokines released from tumor tissues, including CCL2, CCL3, CCL4, CCL5 and CXCL12." (PMID 34925375, 2021).
tumor (continued). "Monocytic-MDSCs express CCR2 and CCR1/CCR5, and can be recruited into tumor tissues by CC chemokines such as CCL2 and CCL5, respectively." (PMID 34885241, 2021). "During circulation, platelet interaction with tumour cells upregulates CCL2 expression on tumour cells and thus promotes vascular permeability." (PMID 34975909, 2021). "MCs also mediate malignant pleural effusion via tryptase and IL-1β release after recruitment via tumor derived CCL2 and activation by osteopontin." (PMID 33418996, 2021). "In vivo experiments have revealed that the administration of anti-CCL2-neutralizing antibodies to severe combined immunodeficient mice subcutaneously injected with VCap cells suppressed tumor growth and macrophage infiltration in tissues." (PMID 34445235, 2021). "Immunostaining showed that CRC cells derived CCL2 govern the macrophage infiltration and polarization in the tumor by interacting with CCR2." (PMID 34580284, 2021). "We identify a peripheral Neuro-Endocrine-Immune pathway in eustress, including Sympathetic nervous system (SNS)/β-adrenergic receptors (β-ARs)/CCL2 that relieves tumor immunosuppression and overcomes PD-L1 resistance to immunotherapy." (PMID 34593796, 2021). "Tumor ECs also recruit TAMs through the production of CCL2, M-CSF, and VEGF which upon entry into the TME promote angiogenesis, immune suppression, and metastasis." (PMID 34987525, 2021). "By interacting with CCR2, CCL2 promotes cancer cell migration and recruits immunosuppressive cells to the tumour microenvironment, favouring cancer development." (PMID 34464477, 2021). "It has been shown that IL-33 promotes tumor invasion by regulating chemokine CCL2 and by recruiting Tregs." (PMID 33390169, 2021). "In an Mmtv-Ccl2 transgenic mouse model, constitutive expression of CCL2 in the mammary glands reduced tumour latency and tumor free survival when challenged with the chemical carcinogen DMBA." (PMID 34771552, 2021). "As shown, EE housing significantly reduced the expression level of CCL2 in the serum and tumor tissues, the effect of which was subverted by blockade of β-ARs signaling." (PMID 34593796, 2021). "In our study, secretion of IL-6, IL-8, MMP-9, PDGF-BB, IL-1β, G-CSF, and CCL-2 by ccRCC immune cells in tumor microenvironment were able to overcome the anti-angiogenic effects of cabozantinib." (PMID 34931665, 2021). "In our in vivo model, however, properdin-deficient mice, when inoculated with logarithmically growing B16F10 cells, showed decreased levels in blood of the chemoattractants C5a and CCL2 and in tumour of the mediators CCL2, CCL3, IL-13, and TIMP-1." (PMID 33494138, 2021). "It is well known that tumor cells or stromal cells in the tumor microenvironment secrete chemokines such as C-C motif chemokine ligand 2 (CCL2), C-X-C motif chemokine ligand 1 (CXCL1), CXCL2, and CXCL5." (PMID 34209505, 2021). "CSF-1, CCL2, 3, 14, and IL-4 are common tumor-derived factors driving the recruitment, proliferation, and M2-polarization of MPs." (PMID 33418996, 2021). "It was shown that CCL2 can be produced by both tumor and myeloid cells, inducing an autocrine loop in the recruitment of TAMs." (PMID 34572939, 2021). "The recruitment of circulating monocytes or macrophages to the tumor tissue is modulated by macrophage chemoattractant molecules such as CCL2 in the TME." (PMID 34207035, 2021). "The gene expression of the chemoattractant CCL2 was also increased, and is known to exert both pro- and anti-tumor effects." (PMID 33809496, 2021). "In the present study, we aimed to prove that CCL2 in distal tissues plays a key role in the construction of the microenvironment before tumor metastasis." (PMID 34249913, 2021). "CCL2 and IL-8 are two potent stimulators of angiogenesis, leading to enhanced tumor vascularization and improved oxygen and nutrient supply to cancer cells." (PMID 34067929, 2021).
tumor (continued). "For example, CCL2 increases RANK expression in osteoclast progenitor cells; CXCL12 has been implicated in homing of ER+ tumor cells to bone." (PMID 34359625, 2021). "In our study, we found that CCL2 circulating levels correlated significantly with the tumor presence and with the abundance of Fusobacterium nucleatum, Bacteroides fragilis and Gemella haemolysans in the colon of our CRC patients." (PMID 34639088, 2021). "Surprisingly, we found that the therapeutic concentration of DIM upregulated the expression level of tumor-related factors such as CCL-2, IL-6, and IL-8 in GC-MSCs." (PMID 33842314, 2021). "Although various targets have been explored to reprogram or deplete tumor-associated macrophages, inhibition of the colony stimulating factor 1 (CSF1) or C-C Motif Chemokine Ligand 2 (CCL2) signaling have been particularly reported." (PMID 34683931, 2021). "At the same time we have observed the increased amount of MCP-1/CCL2 in the plasma of mice bearing the tumours induced by HT29-Snail." (PMID 33419021, 2021). "Ccl2 in the TME of PCa signals self-renewal and recruitment of tumor-associated macrophages (TAMs), myeloid-derived suppressor cells (MDSCs), and T-regulatory cells (Tregs), which lead to immunosuppression and increased angiogenesis." (PMID 34946849, 2021). "Non-coding RNAs have attracted considerable attention owing to their roles in regulating tumor behavior and have been shown to be closely correlated with CCL2 production and TAM reprogramming." (PMID 34386431, 2021). "FAP+-CAFs were isolated by digestion of murine hepatoma tumor tissues and found to be an important source of the chemokine CCL2, which mediates tumor inflammation and immunosuppression." (PMID 34771577, 2021). "By reviewing research on multiple tumor-infiltrating host cells, we have clarified the capability of CCL2 to initiate tumor inflammation." (PMID 34386431, 2021). "A number of preclinical studies have used various CCL2 inhibitors or antibodies to delay tumour progression." (PMID 34464477, 2021). "Neutrophils which exist in tumor microenvironment are capable of producing angiogenic chemokines and cytokines including CCL2,CCL3, CCL5, CCL10, IL4 and IL10 to promote tumor growth, invasion and angiogenesis." (PMID 34123808, 2021). "Strong interactions exist between TNF-α and further mediators such as CCL2, whose expression by tumor cells and macrophages is directly stimulated by TNF-α, thus sustaining a tumor-promoting effect." (PMID 34064859, 2021). "Previous studies in mouse tumour models of post-surgical adjuvant therapy demonstrated that an increase in Ang-2–mediated ICAM-1 expression contributed to the observed increase in CCL2-induced recruitment of tumour-promoting CCR2+Tie2− macrophages." (PMID 33564135, 2021). "Analysis of endogenous expression of GFP in tumor sections revealed that in CCL2 KD tumors, only the peripheral tumor area was viable, and H&E staining showed large necrotic areas in comparison to control tumors at the four-week time-point." (PMID 34824220, 2021). "Infiltration of adipose stromal cells into in tumor tissue enhance CCL2 production, contributing to more recruitment of myeloid-lineage cells." (PMID 34386431, 2021). "More recently, it was reported that FAP promotes immunosuppression through upregulation of CCL2, resulting in increased tumor growth by enhancing recruitment of myeloid-derived suppressor cells and tumor-associated macrophages." (PMID 33996747, 2021). "CCL2 derived from tumour and stromal cells can facilitate lung metastasis by recruiting myeloid cells to lung microenvironments." (PMID 35006432, 2021). "The M-MDSC is attracted to tumor sites by CCL2, CCL5, and CSF1 and PMN-MDSC was attracted by CXCL1, CXCL5, CXCL6, CXCL8, and CXCL12." (PMID 34858479, 2021). "Ccl2 and Ccl7 control the recruitment of monocytes and neutrophils to the inflamed or tumor tissues, while Ccl17 attracts regulatory T cells." (PMID 34504786, 2021).
tumor (continued). "Overall, CCL2 has an unfavorable effect on prognosis in tumor patients because of the accumulation of immunosuppressive cell subtypes." (PMID 34386431, 2021). "We showed that CCL2 was essential for tumor metastasis as it recruits MDSCs to build a microenvironment that promoted metastasis, which was consistent with the results of previous studies." (PMID 34249913, 2021). "Inactivation of neddylation was shown to significantly inhibit CCL2 secretion from lung cancer cells, reducing infiltration of monocytes into the tumor microenvironment and their development into TAMs, ultimately increasing survival." (PMID 34178692, 2021). "A series of elegant mouse studies from Jeffrey Pollard’s group has greatly contributed to our understanding of the biology of MAMs, in particular, how CCL2-mediated recruitment of CCR2+ tumor-promoting inflammatory monocytes facilitates metastasis." (PMID 33924237, 2021). "Tumor cells characterized by the overexpression of homologous protein Six1 can raise the recruitment of TAMs by increasing the expression of CSF-1, CCL2, CCL5, and VEGF, promoting CRC metastasis." (PMID 34326840, 2021). "On one hand, CCL2 can elicit immunosuppressive effects and support tumor progression by promoting increased invasion through angiogenesis, while on the other, it can induce the production of pro-inflammatory cytokines in macrophages to augment their survival." (PMID 34566949, 2021). "CCL2 KD also reduced tumor proliferation by as much as 83%, with an average number of EdU+ cells/mm2 tumor decreased from 458 to 78 per 6 h." (PMID 34824220, 2021). "CCL2 belongs to the CC chemokine family and is secreted by various cells including endothelial cells, fibroblasts, monocytes and tumor cells." (PMID 34335109, 2021). "CCL2 neutralizing antibodies or CCR2 antagonists have been developed to potentiate anti‐tumour effects and have produced encouraging results in some preclinical studies." (PMID 34464477, 2021). "Activation of β-ARs in tumor cells and immune cells directly silenced the CCL2 expression, leading to an immunosuppressive tumor microenvironment and a significant enhancement of checkpoint blockade-refractory tumor response to anti-PD-L1 therapy." (PMID 34593796, 2021). "Concerning BCa, CCL2 was detected in the urine of patients and an increased level was correlated with an increased tumor stage and grade." (PMID 34572939, 2021). "Limiting monocyte infiltration via genetic CCL2 reduction prolongs the survival of tumor-bearing mice." (PMID 34071306, 2021). "M2 macrophages have also been reported to stimulate tumor angiogenesis via CCL-2 and CXCL8, as well as destroy the surrounding tissue matrix by producing tissue enzymes, therefore establishing a prerequisite regulation for cancer cell metastasis." (PMID 34922542, 2021). "The CCR2 and its ligand CCL2 signaling axis are involved in cancer pathogenesis by recruiting immune cells to tumor sites, thereby mediating various immune responses." (PMID 33949150, 2021). "Using a lymphoma mouse model, a study showed that tumor cells educated CAFs to enhance the recruitment of CD11b+Ly6G+ neutrophils via the CCL2-CCR-2 axis and accelerated tumor growth." (PMID 33540679, 2021). "We demonstrated that the high level of endogenous CCL2 expression by A3250 tumor cells was a key factor in driving the inflammatory cell influx in IBC and identified the important function of CCL2 in promoting IBC tumor growth." (PMID 34824220, 2021). "In our study, the greater levels of C5a in tumour-bearing wildtype mice were commensurate with elevated CCL2 levels in this group." (PMID 33494138, 2021). "A previous study involving treatment of murine tumours with tamoxifen suggested tamoxifen abrogated macrophage influx by reducing CCL2/CCL5 levels and reversed macrophage activation." (PMID 34602068, 2021).